CXCL12 (C-X-C motif chemokine ligand 12)
Diseases named in the same sentence as CXCL12 in open-access papers (continued):
Sharing a sentence is not in itself a finding about the gene and the disease.
prostate carcinoma (continued). "Prostate cancer cells express CXCR4, while bone marrow stromal cells produce CXCL12, and prostate cancer cells migrate to the bone marrow partially via interaction with CXCR4." (PMID 31753020, 2019). "The degradation of SDF-1/CXCL12, known to regulate prostate cancer cell metastasis by CD26, is involved in the metastatic cascade of prostate cancer." (PMID 30348967, 2018). "The pro-inflammatory chemokines, including Chemokine (C-C motif) ligand 5 (CCL5 /RANTES), stromal cell derived factor-1 (SDF-1/ CXCL12), and monocyte chemoattractant protein-1 (MCP-1/ CCL2), are often highly expressed in prostate cancer." (PMID 29268703, 2017). "In prostate cancer with bone metastasis, Treg cells expressing high levels of CXCR4 were recruited to bone marrow through an interaction with CXCL12, which is enriched in the bone marrow." (PMID 29379802, 2017). "The CXCL12/CXCR4 axis has been shown to be involved in metastasis of several types of cancers, including prostate cancers." (PMID 27809841, 2016). "For example, CXCL12/CXCR4 was found to be a key regulator of tumor dissemination in cancer cells, including prostate cancer cells and it also plays an important role in the activation of prostate progenitor cells." (PMID 25978029, 2016). "Together, these data showed that acute stimulation by chemokines CXCL11 and CXCL12 changed the intracellular immunoreactivity of CXCR4 and CXCR7 in AD-LNCaP prostate-cancer cells." (PMID 25884570, 2015). "Further experiments focused on characterizing the regulation of CXCL12 and CCL2 across our panel of prostate cancer cells and representative stromal cell lines." (PMID 24970800, 2014). "Similar to chemokine signaling of CXCL12/CXCR4, CXCL12/CXCR7 signaling inhibits apoptosis and increases proliferation and metastasis in prostate cancer." (PMID 24886617, 2014). "While CXCL8 was unable to induce chemokine synthesis in prostate cancer cells, CXCL8 signaling did increase CXCL12 and CCL2 synthesis in prostate stromal fibroblasts and monocytes." (PMID 24970800, 2014). "Our functional experiments establish that CXCL12 and CCL2 act upon prostate cancer cells to induce very different responses." (PMID 24970800, 2014). "CXCL12-induced migration of PC3 cells and CCL2-induced proliferation of prostate cancer cells were dependent upon intrinsic CXCL8 signaling within the prostate cancer cells." (PMID 24970800, 2014). "Using inhibitor assays, we demonstrate that regulation of the PI3K/Akt pathway by PTEN in turn regulates expression of both CXCL12 and CXCR4 in mouse and human prostate cancer cells." (PMID 23902739, 2013). "The chemokine CXCL12, also known as SDF-1, and its receptor, CXCR4, are overexpressed in prostate cancers and in animal models of prostate-specific PTEN deletion, but their regulation is poorly understood." (PMID 23902739, 2013). "Taken together, these studies suggest that targeting the CXCR4/CXCL12 pathway results in decreased prostate progenitor survival in vitro and in vivo in androgen refractory cancer cell lines and potentially could be of therapeutic value against advanced prostate cancers." (PMID 22359577, 2012). "Activation of the CXCR4/CXCL12 signaling pathway significantly increases the CD44+/CD133+ population for both PC3 and DU145 prostate cancer cell lines in a dose dependent manner (up to 3.5-fold and 2.6-fold increase, respectively)." (PMID 22359577, 2012). "The ligand for CXCR4 is CXCL12 (also known as stromal derived factor 1; SDF1) and is highly expressed at sites of prostate cancer metastasis including lymph nodes, bone, lungs and liver." (PMID 21603150, 2011). "We used gain- and loss-of-function approaches to study (i) how SLUG regulates the CXCR4/CXCL12 axis, and (ii) the functional role of CXCL12 in SLUG-induced migration and invasion of human prostate cancer cell lines." (PMID 22074556, 2011).
prostate carcinoma (continued). "MMP9 belongs to the matrix metalloproteinase family and is a target of the CXCL12/CXCR4 signaling in cancer cells, including prostate cancer." (PMID 22074556, 2011). "Although CXCL12 induced VEGF secretion has been reported in various cells, such as lymphohematopoietic cells and prostate cancer cells, CXCL12 induced VEGF production in HCC cells has not been previously studied." (PMID 20380740, 2010). "Our research aims to study CXCL12, CXCR4, MMP-2 and MMP-9 expression in prostate cancer PNI using in vitro experiments, animal model experiments and human prostate cancer tissue." (PMID 18983683, 2008). "CXCL12 and its receptor CXCR4 along with MMP-2 and MMP-9 are related with prostate cancer perineural invasion." (PMID 18983683, 2008). "In the progression of prostate cancer PNI, CXCL12 and CXCR4 secreted by tumor cells and nerve tissue induce tumor cells to migrate toward nerves." (PMID 18983683, 2008). "The effects of exogenous CXCL12 and CXCR4 antagonist AMD3100 on PC3 prostate cancer cells invasiveness were assessed in vitro and in vivo." (PMID 18983683, 2008). "The expression of CXCL12, CXCR4, MMP-2, and MMP-9 in human prostate cancer were higher than those in hyperplastic prostate tissues (P < 0.05)." (PMID 18983683, 2008). "The distribution and expression of CXCL12, CXCR4, MMP-2 and MMP-9 in human prostate cancer and in tumor cells invading nerve tissue were studied with immunohistochemical staining." (PMID 18983683, 2008). "The chemokine stromal derived factor-1 (SDF-1 or CXCL12) and its receptor CXCR4 have been demonstrated to be crucial for the homing of stem cells and prostate cancers to the marrow." (PMID 16859559, 2006). "Studies have confirmed that CXCL12 chemokines and their receptors CXCR4 and CXCR7 may be involved in the initiation and EMT process of prostate cancer metastasis." (PMID 41347146, 2025). "SLUG promotes prostate cancer cell migration and invasion via CXCR4/CXCL12 axis." (PMID 39941741, 2025). "Together, these findings highlight an important role for CAF-derived CXCL12 during tumor progression and chemoresistance, and indicate that inhibition of the CXCL12/CXCR4 signaling axis may chemo-sensitize prostate cancer cells." (PMID 36671452, 2022). "In prostate cancer, the CXCL12/CXCR4 axis is crucial for the initial establishment of bone metastases in the endosteal niche, which is severely compromised by the blockade of the CXCL12/CXCR4 axis." (PMID 35006432, 2021). "The CXCL12/CXCR4 axis is one of the most important axes for the interaction between bone microenvironment and tumor cells and was shown to be important for AKT activation in breast as well as prostate cancer." (PMID 34064589, 2021). "We compared the expression levels of eight integrin subunits (ITGA2, ITGA5, ITGAV, ITGB1, ITGB3, ITGB4, ITGB5, and ITGB6), HOXB13, HOXA11-AS, CCL2, CXCL12, and IBSP in prostate cancer tissues that had metastasized to bone, lymph nodes, lungs, liver, and other organs." (PMID 33514011, 2021). "Treg numbers are increased in prostate cancer patients with bone metastasis, and this may be due in part to active recruitment and retention of Tregs in the bone marrow by CXCR4/CXCL12-mediated signaling, a pathway that is often also upregulated in DTC." (PMID 33805598, 2021). "The activation of CXCL12 chemokine has been reported to increase the motility of LNCaP and PC3 cells and induction of downstream pathways such as Akt-1 and metalloproteinases, which is involved in the regulation of prostate cancer cell migration." (PMID 33808801, 2021).
prostate carcinoma (continued). "According to a recent study, ROSI is capable of downregulating C-X-C motif chemokine 12 (CXCL12)-induced migration, invasion and PI3K/Akt activation in a prostate cancer cell line, through the inhibition of the CXCL12/C-X-C chemokine receptor type 4 (CXCR4) axis." (PMID 34631571, 2021). "A new study regarding prostate cancer bone metastasis demonstrated that prostate cancer cells that produce exosomes can transfer pyruvate kinase M2 (PKM2) into bone marrow stromal cells and up-regulate CXCL12 in these cells." (PMID 32117996, 2020). "In a study to assess the role of the CXCL12/CXCR4 axis in prostate cancer migration and tumor invasiveness, it was reported that CXCL12 activation of prostate cancer cell lines, PC3 and LNCaP, increased their migratory potential via the upregulated expression of several metalloproteinases (MMPs)." (PMID 32585812, 2020). "Furthermore, SLUG can promote prostate cancer cell migration and invasion via activation of the CXCR4/CXCL12 axis." (PMID 33227080, 2020). "In the case of prostate cancer bone metastasis, it has been shown that the bone produces the chemokine CXCL12 (also called stromal-derived factor-1 (SDF-1)), resulting in a gradient of CXCL12 with high levels in the bone compared to the systemic circulation." (PMID 31628348, 2019). "Furthermore, they can be mobilized from these niches in response to inflammatory stimuli, such as CXCL12, CCL5, CCL2, and TGF-β, all of which are upregulated in prostate cancer." (PMID 28493842, 2017). "By blocking the CXCL12/CXCR4 pathway, prostate cancer bone metastasis was significantly suppressed, supporting the hypothesis that prostate tumors metastasize to the bone by adopting this bone-homing signaling pathway." (PMID 25978029, 2016). "To further explore the transactivation of HER2 by CXCL12, we investigated the role of small GTP protein Gαi2 in Src and HER2 phosphorylation in lipid raft membrane microdomains and the significance of CXCR4 in prostate cancer bone tumor growth." (PMID 27809841, 2016). "Conversely, modulation of this tumor suppressor gene had no impact on the expression of either CCL2 or CXCL12 in prostate cancer cells." (PMID 24970800, 2014). "Additionally, prostate cancers typically express high levels of pro-inflammatory chemokines, including CXCL12 (SDF-1), CCL5 (RANTES), and CCL2 (MCP-1)." (PMID 23362217, 2013). "Accumulating data suggest that CXCR4 (CXC chemokine receptor-4) and SDF1 (stroma cell-derived factor-1, or CXCL12) could regulate migration and metastasis in a variety of lung, breast and prostate cancer cells." (PMID 24278179, 2013). "CXCL12 is an important input in CXCR4+ prostate tumor initiating cells and leads to an elevated activation of the PI3K pathway and more robust proliferation of prostate cancer progenitors." (PMID 22359577, 2012). "To determine whether CXCL12/CXCR4 axis plays a role in SLUG-mediated migration and invasion of prostate cancer cells in vitro, we first tested if forced expression of SLUG increases CXCL12 expression." (PMID 22074556, 2011). "In this study, we found that SLUG overexpression upregulated endogenous CXCL12 and increased prostate cancer cell migration and invasion, but reduced adhesion (data nor shown)." (PMID 22074556, 2011). "Therefore, it is unlikely that CXCL12 knockdown impaired SLUG-mediated migration and invasion of prostate cancer cells by promoting cell growth." (PMID 22074556, 2011). "Notably, knockdown of CXCL12 by shRNA impaired SLUG-mediated migration and invasion in prostate cancer cells." (PMID 22074556, 2011). "Thus, our new findings that CXCL12/CXCR4 is a mediator of SLUG-induced migration and invasion of prostate cancer cells provide insight into the molecular mechanisms by which SLUG promotes tumor cell metastasis in vivo." (PMID 22074556, 2011).
prostate carcinoma (continued). "Knockdown of SLUG decreased CXCL12 and CXCR4 expression in prostate cancer cells." (PMID 22074556, 2011). "In order to identify genes that are regulated by CXCR4 and contribute to the aggressive phenotype of CXCR4-expressing prostate cancer, we compared the expression pattern of various chemokines between CXCL12-stimulated and non-stimulated PC3-CXCR4.5 cells." (PMID 19340288, 2009). "The study was the first time to report the roles of CXCL12 and CXCR4 in PNI of prostate cancer." (PMID 18983683, 2008). "First, because CXCL12 up regulates CD164 expression and stimulates prostate cancer cell proliferation and adhesion, therapies designed to disrupt CD164 or the CXCL12/CXCR4 axis could be used to alter tumor progression via several mechanisms." (PMID 16859559, 2006). "The CXCL12 and chemokine receptors, CXCR4 and CXCR7, are the key factors that link cancer cells and their microenvironment, thus playing a crucial role in tumor initiation and progression, including the migration of prostate cancer cell lines such as PC3 and LNCaP." (PMID 37050202, 2023). "Therefore, interruption to the level of CXCL12 and disruption to CXCL12-CXCR4 litigation could possibly lead to the inhibition of prostate cancer cells migration and invasion." (PMID 29326585, 2017). "Moreover, the release of CXCL8 from PTEN-depleted prostate cancer cells may act in a paracrine manner to increase the expression and secretion of CCL2 and CXCL12 from neighboring stromal cells." (PMID 24970800, 2014). "Increased expression and activity of CCL2 and CXCL12 has been reported in both the localized prostate cancer and within the microenvironment of bone metastases, while prior work from our own group has confirmed elevated CXCL8 expression in human prostate cancer tissue." (PMID 24970800, 2014). "We demonstrated that forced expression of SLUG elevated CXCR4 and CXCL12 expression in human prostate cancer cell lines PC3, DU145, 22RV1, and LNCaP; conversely, reduced expression of SLUG by shRNA downregulated CXCR4 and CXCL12 expression at RNA and protein levels in prostate cancer cells." (PMID 22074556, 2011). "Prostate cancer cells with significant CXCR4 expression may escape from primary tumor foci, enter into the lymphatic and blood vessels and migrate toward cells expressing CXCL12." (PMID 18983683, 2008). "Our research demonstrated that the expression of CXCL12, CXCR4, MMP-2, and MMP-9 in prostate cancer was much higher than in hyperplastic prostate tissue, implying that these proteins interact with each other and together may regulate chemotactic ability and invasiveness of tumor cells." (PMID 18983683, 2008). "The flavonol myricetin could suppress the CXCL12-CXCR4 axis in human prostate cancer cells PC-3 via inhibiting the activity of Moloney murine leukemia virus 1 (PIM1) and disrupting its interaction with CXCR4, leading to a significant decrease in CXCL12-induced cell migration." (PMID 39465008, 2024). "Our experiments revealed that antibodies that recognize CD164 inhibited the binding of prostate cancer cells to human bone marrow endothelium and reduced invasion of the extracellular matrix by prostate cancer cells, irrespective of whether the cancer cells were stimulated by exposure to CXCL12." (PMID 16859559, 2006). "Our initial data suggests that stromal rather than prostate cancer cells are the principal source of CCL2 and CXCL12." (PMID 24970800, 2014). "Lastly, our data suggest that CXCL12 and SLUG regulate migration and invasion of prostate cancer cells independent of cell growth." (PMID 22074556, 2011). "Lastly, we provide evidence that CXCL12 and SLUG regulate migration and invasion of prostate cancer cells independent of cell growth." (PMID 22074556, 2011). "Because CXCL12 shRNAs relieve SLUG-mediated migration and invasion of prostate cancer cells, we asked whether or not cell proliferation plays a role in these processes." (PMID 22074556, 2011).
pancreatic cancer (182 papers, 2007 to 2026). "For example, targeting CXCL12 to antagonize the development of pancreatic cancer associated with FAP-expressing cancer-associated fibroblasts." (PMID 40264753, 2025). "Surprisingly, in previous studies, it has been proved that all of our defined switch genes, including Lamc2, Klk1, Nqo1, Aox1, Tspan1, and Cxcl12, are closely associated with the pancreatic cancer’s progression." (PMID 35180880, 2022). "To define the role of CXCL12 and CXCR4 in the progression of pancreatic cancer, we analyzed the association of expression profiles of CXCL12 and CXCR4 with tumor grade and stage." (PMID 23181100, 2012). "Here, we examined the expression of CXCR4 and its ligand CXCL12 by immunoblot and enzyme-linked immunosorbant assay (ELISA), respectively, in a panel of 12 pancreatic cancer cell lines." (PMID 21045835, 2010). "In pancreatic cancer, the inhibition of CXCL12 derived from carcinoma-associated fibroblasts could induce rapid T cell accumulation among cancer cells and play a synergistic role with anti-PD-L1 to kill cancer cells." (PMID 35468838, 2022). "This overview focuses on a chemokine, CXCL12, produced by cancer-associated fibroblasts and how CXCL12 signaling enhances pancreatic cancer progression by contributing to various hallmarks of cancer including, but not limited to, tumor growth and evasion of immune response." (PMID 35008248, 2021). "PSC-derived CXCL12, deoxycytidine, and fibronectin were reported to promote drug resistance in pancreatic cancer; however, the underlying mechanism remains unclear." (PMID 34849465, 2021). "Accordingly, the chemoattracting effect of CXCL12 on CXCR4+ pancreatic cancer cells might reflect a major cause for the formation of metastases directly where CXCL12 is highly expressed such as in lymph nodes, in the liver, lungs, and bone marrow." (PMID 26091099, 2015). "However, in pancreatic cancer the CXCL12/CXCR4 axis has been functionally implicated in tumor progression by initiating tumor cell migration, invasion, angiogenesis, and putatively inducing metastasis." (PMID 26091099, 2015). "CXCL12 has downstream effects on cancer cell proliferation, as well as myeloid cell and T‐cell recruitment and targeting CXCL12 synergises with checkpoint blockade in pancreatic cancer." (PMID 39743376, 2025). "CXCL12 has been shown to be abundantly secreted by CAFs to confine CTLs to the stroma and suppress their motion into pancreatic tumours." (PMID 39931761, 2025). "In contrast, the CXCL12/CXCR4 axis is involved in the retention of T cells in the tumor stroma of pancreatic cancer." (PMID 38335302, 2024). "Apart from direct pro-tumorigenic functions on pancreatic cancer cells, CXCL12 is also heavily involved in mediating the metastasis of pancreatic cancer cells." (PMID 38339310, 2024). "This increase in CXCR4 by pancreatic cancer cells, leading to increased CXCL12 production by CAFs, has also been documented by others." (PMID 38339310, 2024). "Early pancreatic cancer lesions suppress pain through CXCL12‐mediated chemoattraction of Schwann cells." (PMID 39346791, 2024). "An experimental study in pancreatic cancer showed that CXCL12 interrupts the growth and metastasis of primary tumor through cell-cycle arrest, ultimately leading to an increase in overall survival." (PMID 37966614, 2023). "Another study on pancreatic cancer showed that radiation stimulates CAFs to secrete high concentrations of CXCL12 and act on pancreatic cancer cells through CXCR4, directly promoting EMT and tumor cell invasion." (PMID 37607935, 2023). "An elevation of CXCL12 secretion is also confirmed in irradiated CAFs, with a stimulating effect on pancreatic cancer cell migration, invasion, and EMT-related drug resistance." (PMID 35488263, 2022). "In this regard, a crucial study has demonstrated that targeting CXCL12 from FAP+ CAFs with plerixafor (AMD3100) synergizes with anti-PD-L1 treatment in pancreatic cancer." (PMID 36338519, 2022).